TNF (tumor necrosis factor)
Diseases named in the same sentence as TNF in open-access papers (continued):
Sharing a sentence is not in itself a finding about the gene and the disease.
astrocytoma (continued). "The secretion of tumour necrosis factor-α (TNFα),interleukin-1α (IL-α) and interleukin-6 (IL-6) by ahuman astrocytoma cell fine was studied 1 h, 3 h, 6 h and 24 h afterinfection with tachyzoites from three Toxoplasma gondiistrains (virulent, RH; cystogentc, 76K and Prugniaud strains)." (PMID 18472955, 1994). "We did not study inflammation in the present investigation, but it has been reported that neuroinflammatory stimuli, which include the cytokines TNFα and IL1, can induce RPTPγ transcription in astrocytomas." (PMID 38952869, 2024). "Infection with RVFV induced significant upregulation of ATF3, FOS, KLF4, CXCL10, TNF-α, and PTGS2 in astrocytoma cells at 16 hpi." (PMID 35746681, 2022). "CHIKV infection in astrocytoma cells produced a robust induction of CXCL10 and TNF-α, two inflammatory genes well documented for their role in enhancing the severity of disease in human cases as well as in mouse models of infection." (PMID 35746681, 2022). "Astrocytoma cell line U373-MG and primary astrocytes express PTPRG whose expression was found to be regulated by IL-1 or TNFα." (PMID 35071225, 2021). "In an astroglial cell culture model, addition of tumor necrosis factor-alpha (TNF-α) and FTY720-P to human primary embryonic astrocytes and astrocytoma cultures was used to mimic an inflammatory milieu in the CNS." (PMID 28913617, 2017). "The selective CK2 inhibitor CX-4945 significantly reduced the IL-1β/TNF-α induced secretion of the inflammatory cytokines MCP-1 and IL-6 both in human primary astrocytes and U373 astrocytoma cells in a dose-dependent manner." (PMID 26732432, 2016). "It was shown that the astrocytoma cell line U87 expressed and released increased amounts of NGF in response to 50 pg/ml of exogenous TNFα." (PMID 25841889, 2015). "Through comprehensive analysis-including RT-qPCR, ELISA, immunohistochemistry, methylation profiling, miRNA expression, and survival analysis, we demonstrate that TNF-α, IL-1 β, and MAP3K8 are not only upregulated in high-grade astrocytomas but also independently predict worse overall survival." (PMID 40565357, 2025). "In addition, astrocytoma exhibited activated epithelial mesenchymal transformation (EMT) and dMMR, TGF-β and TNF pathway functions." (PMID 35287567, 2022). "In rat astrocytoma cell line, lipopolysaccharide (LPS) could increase NO, ROS, malondialdehyde (MDA), and decrease reduced-glutathione (GSH), while tumor necrosis factor-α (TNF-α) was increased by LPS in a human monocytic leukemia cell line." (PMID 28212342, 2017). "However, TNF-α has been reported to down-regulate expression and secretion of MMP-2 from both astrocytoma and choroid plexus epithelial cells." (PMID 21569377, 2011). "Infection of astrocytoma cells with SINV, another Old World alphavirus, significantly induced transcription of CXCL10 and TNF-α, but neither were dependent on EGR1." (PMID 35746681, 2022).
chronic myeloid leukemia (30 papers, 2010 to 2025). "The top 20 most significantly enriched signaling pathways included DNA replication, the TNF signaling pathway, the NF-κB signaling pathway, cellular senescence, endocrine resistance, chronic myeloid leukemia, and T-cell leukemia virus type 1 infection." (PMID 40431657, 2025). "Genes annotated to H3K27ac lost peaks were significantly enriched in pathways involved in differentiation, signal transduction, chronic myeloid leukemia, and TNF signaling." (PMID 34622806, 2021). "Compound 257 dose-dependently down-regulated TNFα (Tumor Necrosis Factor) -induced NF-κB (Proteins that can regulate gene expression) activity in human chronic myeloid leukemia cells with an IC50 of 38.5 ± 1.2 μM." (PMID 32075151, 2020). "STAT3 dephosphorylation can sensitize doxorubicin-resistant Dalton lymphoma to dendritic cell (DC)-derived TNF-α through the downregulation of Bcl-2 upon cucurbitacin I (STAT3 inhibitor) treatment in DC (chronic myeloid leukemia) patients." (PMID 32872659, 2020). "We observed that the combination of bergamottin and simvastatin produced synergistic effects on the tumor necrosis factor (TNF)-induced cytotoxicity and apoptosis in human chronic myelogenous leukemia KBM-5 cells." (PMID 30558157, 2018). "Compounds 1, 2 and 4 dose-dependently down-regulated TNFα-induced NF-κB activity in human chronic myeloid leukemia cells with IC50s of 38.5 ± 1.2 μM, 65.7 ± 2.0 μM and 82.7 ± 11.3 μM, respectively." (PMID 26258781, 2015). "Additionally, XN regulates the anti-angiogenic effects of NF-κB by suppressing the level of MMP-9, VEGF, and ICAM-1 stimulated by TNF in chronic myelogenous leukemia." (PMID 38611849, 2024). "As for KEGG, we obtained 58 terms, including “insulin signaling pathway,” “cAMP signaling pathway,” “insulin resistance,” “chemokine signaling pathway,” “chronic myeloid leukemia,” “adrenergic signaling in cardiomyocytes,” and “TNF signaling pathway” in the top 30 terms." (PMID 35935642, 2022). "In addition, at 24 hpi, the cAMP, NF-κB, and TNF signaling pathways, Fc gamma R-mediated phagocytosis, B-cell receptor signaling pathway, and chronic myeloid leukemia were involved." (PMID 35516441, 2022). "Similarly, a previous study revealed that the supernatant of human-derived Lactobacillus reuteri promotes tumor necrosis factor (TNF)-induced apoptosis of human chronic myeloid leukemia cells through p38 activation." (PMID 32238777, 2020). "Interestingly, TNF-α signaling has been shown to be involved in cancer progression and survival of chronic myeloid leukemia." (PMID 27276704, 2016). "TQ has been reported to suppress tumor necrosis factor (TNF) induced NF-κB expression in human chronic myeloid leukemia cells (KBM-5) which may also explain why cells undergo apoptosis." (PMID 20594324, 2010). "Meanwhile, FAN effectively suppresses NF-κB activation induced by tumor necrosis factor-α (TNF-α) through attenuating phosphorylated IκB kinase (IKK) and p65 in human chronic myeloid leukemia cells (KBM5 cells)." (PMID 39000284, 2024). "Doxorubicin-resistant chronic myeloid leukemia cells enhanced phosphorylation of STAT3 and dampened the tumor growth inhibition of TNF-α." (PMID 32872659, 2020). "In another study, Chronic Myeloid Leukemia (CML)-derived small EVs have been shown to induce M2-like macrophage polarization leading to IL-10 and TNF-α overexpression." (PMID 31137912, 2019). "Tumor necrosis factor (TNF)-related apoptosis-inducing ligand (TRAIL) and resveratrol were observed to stimulate autophagic cell death in breast epithelial cells and chronic myelogenous leukemia cells, respectively, via AMPK activation and the suppression of downstream mTOR signaling." (PMID 31547619, 2019).
histoplasmosis (30 papers, 2009 to 2025). A disease caused by the fungus Histoplasma capsulatum. "This is a systematic review and meta-analysis of studies that contain parameters for calculating the risk of histoplasmosis in people who use TNF-α inhibitors, to produce a risk estimate." (PMID 38065857, 2023). "This study aimed to produce an updated risk estimate of histoplasmosis in patients on TNF-α blocking therapy." (PMID 38065857, 2023). "In a survey of infectious disease specialists, histoplasmosis was second only to S. aureus as the cause of serious infection complicating anti-TNF and other BRM." (PMID 28702025, 2017). "More recently, treatments with inhibitors of tumor necrosis factor-α have been shown to place patients at high risk for developing histoplasmosis." (PMID 22007223, 2012). "Immunomodulatory therapies, including anti-TNF agents and CS, pose a risk for development of histoplasmosis." (PMID 21605439, 2011). "We describe the occurrence and risk factors for histoplasmosis in adult patients with RA in an endemic region in the era of anti-TNF therapies." (PMID 21605439, 2011). "Resumption of immunomodulatory therapies including anti-TNF therapy must be undertaken cautiously in patients who developed histoplasmosis while on anti-TNF therapy as there is a risk of serious relapse of the infection despite suppressive antifungal therapy." (PMID 21605439, 2011). "The risk of histoplasmosis during TNF-α inhibitory therapy may be considerably higher than that found in classical estimates, especially in patients with IBD." (PMID 38065857, 2023). "Histoplasmosis is the most common IFI associated with TNF-α inhibitors." (PMID 28702025, 2017). "The risk of reactivation of severe histoplasmosis is unknown for any patient who was previously treated for the infection and who is then re-challenged with anti-TNF agents despite chronic azole therapy." (PMID 21605439, 2011). "While multiple types of immunosuppressive medications may be associated with an increased risk of histoplasmosis, patients receiving TNF-α inhibitors (infliximab, etanercept, adalimumab, certolizumab, golimumab) are at the highest risk of intracellular infections, including histoplasmosis." (PMID 36836350, 2023). "This association resulted in an FDA warning, issued on September 4, 2008, that notified healthcare professionals the recognition of histoplasmosis in patients taking anti-TNF agents may be associated with delays in treatment that can ultimately result in death." (PMID 21605439, 2011). "The increasing use of biologic agents, such as TNF-α inhibitors, has also contributed to the rising incidence of histoplasmosis in immunosuppressed patients." (PMID 40137234, 2025). "This difference in the occurrence of histoplasmosis between different types of TNF-α inhibitor drugs was a tendency suggested since the first reports." (PMID 38065857, 2023). "Histoplasmosis also appears to be a treatment complication in some safety databases of TNF-α inhibitory drugs." (PMID 38065857, 2023). "In 2008, a cluster of histoplasmosis cases among patients receiving TNF-α inhibitors led the United States Food and Drug Administration (FDA) to issue a Boxed Warning." (PMID 36104715, 2022). "Histoplasmosis is the most prevalent IFD in patients undergoing TNFα inhibitors therapy, followed by candidiasis and aspergillosis." (PMID 30562960, 2018). "The incidence of histoplasmosis appears to be higher in patients treated with anti-TNF monoclonal antibodies (e.g., infliximab) than in patients receiving soluble TNF-α receptors (e.g., etanercept)." (PMID 30562960, 2018). "TNF-α is a key modulator of disease in both primary and secondary histoplasmosis, though different protective mechanisms are involved in these conditions." (PMID 22007223, 2012). "For the majority of patients on anti-TNF agents in our study, the therapy was discontinued at diagnosis and withheld throughout the period of histoplasmosis treatment." (PMID 21605439, 2011).
histoplasmosis (continued). "More than 50% of RA patients who developed histoplasmosis during the 11 year study period were on anti-TNF treatment." (PMID 21605439, 2011). "Ten cases of histoplasmosis in patients taking anti-TNF agents from post licensure surveillance from the Adverse Event Reporting System (AERS) of the Food and Drug Administration (FDA) have been published." (PMID 21605439, 2011). "Other infections occurring during TNFα antagonist therapy include legionellosis, listeriosis, pneumocystosis, histoplasmosis, and aspergillosis." (PMID 19886992, 2009). "On the other hand, histoplasmosis also occurs in patients with other immunosuppressive conditions such as autoimmune diseases, chronic pulmonary obstructive disease, asthma requiring an inhaler, heart disease, people who use TNF-α inhibitors, and cancer." (PMID 40137234, 2025). "In conclusion, we found that most patients who were hospitalized with histoplasmosis in the past decade and who were immunocompromised had received a solid organ transplant or were being treated with TNF antagonists or other disease-modifying anti-rheumatic drugs." (PMID 41003217, 2025). "Discontinuation of TNFα inhibitors results in IRIS in 9.2% of patients with histoplasmosis." (PMID 30562960, 2018). "This case report displays that although HI was not previously confirmed, its development could be explained from the existing evidence related to anti-TNFα therapy where reactivation of Histoplasmosis has been described." (PMID 25379301, 2013). "Anti-TNF treatment was restarted in 4/15 patients, with recurrence of histoplasmosis in one." (PMID 21605439, 2011). "If a patient has been diagnosed with histoplasmosis during the 2 years preceding TNF-α blocker therapy, or if the clinical, radiographic, or laboratory findings suggest the patient may have had histoplasmosis during that interval, present guidelines suggest to consider antifungal prophylaxis." (PMID 36104715, 2022). "Significant differences in the median values of IL-1β, TNF-α, IFN-γ, IL-18, IL-17A, IL-33, IL-13, and CXCL8 were reached in all the groups studied, suggesting that these cytokines play a role in the inflammatory processes associated with histoplasmosis and pneumocystosis." (PMID 34829225, 2021). "In this meta-analysis, relation between elevated risk of TB, histoplasmosis and anti-TNF drugs, could not be found." (PMID 30658717, 2019). "Moreover, in experimental histoplasmosis, depletion of GR-1+ cells, primarily neutrophils, promotes the increase in fungal load in the lungs and spleens and decreases the survival of animals even in the presence of high levels of TNF-α and NO." (PMID 27698545, 2016). "How to screen for histoplasmosis and manage the patient with RA who has potential histoplasma exposure, lives in an endemic area for histoplasmosis, or has had previous overt histoplasmosis and requires immunomodulatory therapy, including anti-TNF treatment may be answered by further studies." (PMID 21605439, 2011). "The HIV pandemic and the increasing use of immunosuppressive medications, such as calcineurin and tumor necrosis factor (TNF) inhibitors, have resulted in a rising trend of histoplasmosis and coccidioidomycosis in endemic regions." (PMID 28702025, 2017). "Although cytokine responses are complex in histoplasmosis and alter over the course of disease, the main cytokines involved in Histoplasma clearance from the host are IL-12, IFN-γ, and TNF-α." (PMID 22007223, 2012). "Elevated IL-1β, TNF- α, IL-18, and PTX3 levels in HIV patients with histoplasmosis could serve as a potential predictive biomarker for poor prognosis and disseminated disease development in these individuals." (PMID 40558960, 2025). "Despite the large number of patients using TNF-α inhibitors in clinical practice, there is still no systematic review of the medical literature regarding the incidence of histoplasmosis in this population." (PMID 38065857, 2023).
histoplasmosis (continued). "The patient recovered from the histoplasmosis, and the anti-TNF therapy was not subsequently restarted." (PMID 21605439, 2011). "The patient's anti-TNF treatment (infliximab) was continued without interruption, and without development of overt histoplasmosis." (PMID 21605439, 2011). "In our study, TNF-α and IL-1β together with IL-6 and IL-18 showed the highest values, with statistical differences for the group of HIV patients and Hc suggesting that these cytokines play a role in the local inflammatory processes of histoplasmosis in HIV patients." (PMID 40558960, 2025). "The increased values of TNF-α in the Non-HIV-Hc group could be due to an acute lung inflammatory response to histoplasmosis." (PMID 34829225, 2021). "Significant differences in median values of SP-A, IL-1β, TNF-α, IFN-γ, IL-18, IL-17A, IL-33, IL-13, and CXCL8 were found among all the groups studied, suggesting that these cytokines play a role in the local inflammatory processes of histoplasmosis and pneumocystosis." (PMID 34829225, 2021). "Though chest radiography may not predict reactivation of histoplasmosis in patients on TNF-inhibitors, we believe it is valuable to determine pre-existing abnormalities in all patients in whom immunomodulatory therapy, including CS, conventional DMARD and biologic response modifier therapies." (PMID 21605439, 2011).
inflammatory bone diseases (30 papers, 2013 to 2026). "TNF-α also plays an important role in bone metabolism and is associated with inflammatory bone diseases." (PMID 35163403, 2022). "It is reported that dysregulation of LEPROT is associated with various bone inflammation diseases through key cytokines, such as tumor necrosis factor alpha (TNF-α) and interleukin 6 (IL-6)." (PMID 34804118, 2021). "TNF-α is a strong apoptosis inducer and a proinflammatory cytokine that contributes to bone loss in local and systemic inflammatory bone diseases." (PMID 30515223, 2018). "By contrast, in inflammatory bone diseases, osteoblast activity is suppressed through mechanisms such as TNF- and DKK1-mediated inhibition." (PMID 41559024, 2026). "GV infection caused osteitis, leading to a notable increase in the expression of RANK, RANKL, TNF-α, IL-6, TRAP, and MMP-2 in the femur, accompanied by an increase in the number of TRAP+, TNF-α+, and RANK+ cells, while osteoprotegerin expression decreased." (PMID 40284791, 2025). "The pro-inflammatory cytokine, tumor necrosis factor-alpha (TNF-α) is considered a potent inducer of bone resorption and plays a crucial role in bone metabolism and inflammatory bone diseases." (PMID 39022305, 2024). "The well-documented role of TNF-α in bone inflammatory diseases is to promote bone resorption and contribute to disease progression." (PMID 35163403, 2022). "In contrast with the destructive polysynovitis observed in classical TNF overexpression models, mice overexpressing tmTNF developed axial and peripheral joint disease with synovitis, enthesitis, and osteitis." (PMID 32662821, 2020). "The combination of vancomycin treatment and HBO therapy did not lead to a significant reduction of the bacterial load, the histo-pathologically evaluated degree of osteitis and IL-1b, IL-10, and TNF-a levels, in comparison to vancomycin treatment alone." (PMID 29377928, 2018). "In this study, we revealed the inhibitory effect of (D-Ala2)GIP on TNF-α-induced osteoclast formation and bone resorption in vivo, highlighting the potential of targeting GIP signaling as a therapeutic strategy for TNF-α-associated inflammatory bone diseases." (PMID 41516077, 2025). "Like many chronic inflammatory states in the bone microenvironment, TLR4 activation plays a crucial role in producing various pro-inflammatory cytokines such as TNF-α, IL-6, and IL-1β in macrophages, which stimulate OC formation and contribute to the pathology of inflammatory bone diseases." (PMID 37596575, 2023). "This process is orchestrated via other pro-inflammatory cytokines such as IL-1 and TNF-α in inflammatory bone diseases in vivo by stimulating OC formation from macrophages directly and inducing RANKL production in pre-osteoblasts (pOBs) to enhance OC forming potential." (PMID 37596575, 2023). "In inflammatory bone diseases, elevated systemic levels of TNF can stimulate the generation of osteoclast precursors (OCPs) in the bone marrow and can also enhance their egress into the bloodstream, through which inflammatory responses can be maintained and even amplified." (PMID 32211607, 2020). "Interestingly, simvastatin reduced TNF-α-induced synthesis of Cysteine-rich 61 (Cyr61) and chemokine ligand 2 (CCL2) that are potential osteolytic mediators in inflammatory bone diseases, in human OB, thereby decreasing bone loss." (PMID 30936777, 2019). "Macrophages are the major source of TNF-α in inflammatory bone diseases." (PMID 25144740, 2014). "TNF-α is also elevated in the bone inflammatory patients and may exert as a major mediator in bone inflammatory diseases." (PMID 24502696, 2014). "Matrix metalloproteinase-9 (MMP-9) has been shown to be induced by cytokines including TNF-α and may contribute to bone inflammatory diseases." (PMID 24502696, 2014). "Elucidating the detailed effects of TNF-α on bone metabolism may enable the identification of therapeutic targets that can efficiently suppress bone destruction in inflammatory bone diseases." (PMID 23762085, 2013).